NECTIN2 (nectin cell adhesion molecule 2)
Diseases named in the same sentence as NECTIN2 in open-access papers (continued):
Sharing a sentence is not in itself a finding about the gene and the disease.
tumor (continued). "Our analysis revealed the correlation between PVR and NECTIN2 expression and the tumor immune microenvironment or tumor microenvironment in cancer, and further solidified the critical role of PVR and NECTIN2 in tumor immune regulation." (PMID 39120585, 2024). "We observed that the percentage of PLOD2 + SAA1 + tumor cells with high MECRGS scores, as well as the expression of immune checkpoints such as NECTIN2 and CD47, increased in patients who exhibited a partial response (PR) to immunotherapy." (PMID 38951896, 2024). "In particular, we found that the NECTIN2-TIGIT immune coinhibitory interactions, mediated by the NECTIN2 ligand expressed on tumor cells and the TIGIT receptor expressed on immune cells, were prevalent during the histologic progression." (PMID 39474422, 2024). "Across most tumor types, there exists a robust correlation between PVR and NECTIN2 expression and infiltration of epithelial cells." (PMID 39120585, 2024). "Gene expression levels of ANXA1-FPR3, NECTIN2-TIGIT, CXCL8-NR3C1, LGALS9-HAVCR2, C5AR1-RPS19, and SPP1-PTGER4 pairs were higher in sender and receiver cells derived from tumor tissue compared with normal tissue." (PMID 38002057, 2023). "TIGIT has two ligands, CD155 (PVR) and CD112 (PVRL2, nectin-2), which are expressed by antigen-presenting cells and tumor cells in TME to decrease the activity of T cells and NK cells." (PMID 37129788, 2023). "The three nectin and NECL molecular family proteins CD155(PVR), CD112(PVRL2 or Nectin-2), and CD113 (Nectin-3), which are expressed on tumor cells or antigen-presenting cells, are the known TIGIT ligands." (PMID 36135216, 2022). "Endothelial and tumor cells mainly secreted poliovirus receptor (PVR) and NECTIN2, which acted on the TIGIT receptor on the surface of Tex." (PMID 36685571, 2022). "TIGIT also suppresses anti-tumor immunity by TCR downregulation upon the binding to the ligands, CD155 (PVR) and CD112 (Nectin2), expressed in myeloid cells and tumor cells." (PMID 36211375, 2022). "It was reported that nectin-2 binds to PVRIG on NK and T cells, thereby limiting their anti-tumor activity." (PMID 36293219, 2022). "TIGIT binds to two ligands, CD155 (PVR) and CD112 (PVRL2, nectin-2), that are expressed by tumor cells and antigen-presenting cells in the tumor microenvironment." (PMID 35222404, 2022). "TIGIT has many ligands, CD155 (PVR or Necl-5), CD112 (nectin-2, also known as PRR2 or PVRL2), and CD113, CD155, CD112, CD113, and CD111, which are expressed in APCs or tumor cells." (PMID 35669786, 2022). "TIGIT binds with high-affinity to CD155 (PVR) and with low-affinity to CD112 (PVRL2; nectin-2) which are expressed in the tumor microenvironment (TME) by antigen presenting cells (APCs) and tumor cells." (PMID 34025646, 2021). "In these immunosuppressive marker genes, TGFB1, NECTIN2, LGALS9, LAG3, and IL10RB were significantly correlated with CCDC137 expression in most tumor types." (PMID 34055889, 2021). "TIGIT is expressed by activated T-cells, NK cells, and Tregs, and its ligands include CD112 (NECTIN2) and CD155 (Necl-5), which are expressed by tumor cells and APCs within the tumor microenvironment (TME)." (PMID 34943817, 2021). "NK–tumor interactions included HLA-C/KIR2DL4, HLA-E/CD94 (KLD1), TIM3 (HAVCR2)/Galectin-9, CD96-PVR/Nectin1 and TIGIT-PVR/Nectin2." (PMID 33671917, 2021). "CD112 (cluster of differentiation 112), also known as nectin-2 or PVR-related protein 2 (PVRL2), is a member of the nectin family and has been repotored to correlate with tumor angiogenesis, growth, and metastasis." (PMID 34507594, 2021). "Nonetheless, efficient tumor cell killing requires additional activating signaling, such as that of DNAM-1 (CD226) interacting Nectin-2 (CD112) and poliovirus receptor (PVR or CD155) ligands." (PMID 34064810, 2021). "Expression of CD112 (nectin-2) and CD155 (poliovirus receptor; PVR), which are NK cell activating ligands, is increased in virus-infected cells and tumor cells." (PMID 33256093, 2020).
tumor (continued). "The ligands of DNAM-1 are CD112 (nectin-2, PRR2) and CD155 (PVR, Necl4), which are expressed in some immune cells such as monocytes, DCs, activated CD4+ T cells, and tumor tissue." (PMID 32774149, 2020). "As is shown in the multi-colour immunofluorescence staining analysis of 135 GC tissues, ~90% of tissues show that NECTIN2, CEACAM1, HMGB1, SIGLEC6 and CD15 were expressed in tumour cells, and CD44 was expressed in tumour cells in about 70% of tissues." (PMID 33311518, 2020). "Compared to non-tumor tissues (N), a variety of factors like TGF-β1, TGF-β2, HMGB1, PVR, nectin-2, galectin-9, PD-L1, PD-L2, and MICA/MICB were significantly higher in the tumor tissue (T)." (PMID 31234517, 2019). "CD112R specifically binds nectin-2 with high affinity and blockade of CD112R increased NK cell anti-tumor response." (PMID 30759143, 2019). "Inhibition of Ub and SUMO pathways increases Nectin2 and PVR surface expression and renders tumor cells more sensitive to NK cell-mediated killing." (PMID 31736972, 2019). "NK cells also express members of the immunoglobulin (Ig) superfamily such as the activating receptor DNAM-I, which has been shown to recognize CD112 (PVR) and CD155 (Nectin-2), two ligands expressed on tumor cells." (PMID 31474977, 2019). "To determine if differential receptor expression contributed to this discrepancy, we analyzed these tumor cells by flow cytometry for cell surface expression of three known HSV receptors, HVEM, nectin-1 and nectin-2." (PMID 29765544, 2018). "In this report, we assessed the toxicity of Y-443, a fully human IgG1/kappa anti-Nectin-2 monoclonal antibody exhibiting strong in vitro ADCC and in vivo anti-tumor activity in cynomolgus monkeys (Macaca fascicularis (Cynos))." (PMID 29723247, 2018). "TIGIT binds two ligands, CD112 (PVRL2, nectin-2) and CD155 (PVR), and these ligands are expressed by T cells, APCs, and tumor cells." (PMID 28545567, 2017). "DNAM-1 is preferentially expressed on NK cells and CD8 T cells and has been involved in improved cytotoxic function of these cell types towards tumor cells expressing DNAM-1 ligands CD155 (poliovirus receptor) and CD112 (nectin-2)." (PMID 26880996, 2016). "CD112 (Nectin-2, PVRL2) and CD155 (Necl5, PVR) bind CD226 (DNAM-1), which potentiates in vitro the cytotoxicity of NK cells against a wide range of tumor cells; CD58 (LFA-3) binds CD2 and its co-engagement with ICAM-1 increases NK response." (PMID 26106390, 2015). "The anti-Nectin-2 mAb Y-443, representing epitope bins VII, showed in vivo anti-tumor effects on OV-90 and MDA-MB-231 cells, and all the experimental results suggested that ADCC is the main mechanism of action of Y-443." (PMID 23758976, 2013). "It binds to its ligands CD155 (PVR) or NECTIN-2 (CD112), which are frequently overexpressed on malignant or antigen-presenting cells (APCs), TIGIT suppresses cytotoxic immune responses, contributing to immune evasion within the tumor microenvironment (TME)." (PMID 40799645, 2025). "Blocking Nectin2 improved CD8+ T-cell function and suppressed tumor progression in the mouse model." (PMID 39261943, 2024). "In addition, TIGIT has been found to bind three ligands, namely CD155 (PVR), CD112 (PVRL2, nectin-2), and CD113 (PVRL3), which are expressed by tumor cells, antigen-presenting cells, and also T-lymphocytes in the tumor microenvironment." (PMID 36765782, 2023). "The high expression of NECTIN-2, the ligand of PVRIG, which has also been reported by others in HCC tumors, might bridle anti-tumor response efficiency." (PMID 36672396, 2023). "Vδ2+ T cells are activated by cells that accumulate HMBPP and/or IPP and can also be stimulated through receptors NKG2D and DNAM-1 of various stress-induced molecules expressed on tumor cells including MICA/B, UL16-binding proteins (ULBP1–6), Nectin-2, and PVR, respectively." (PMID 36851283, 2023). "Urine levels correlated with tumor expression and serum levels in the Nectin-4 analysis, but not in the Nectin-2 analysis." (PMID 37174031, 2023).
tumor (continued). "Tumor cells mainly secreted PVR and NECTIN2 to act on the TIGIT receptor." (PMID 36685571, 2022). "TIGIT competes with the immunoactivator receptor CD226 (DNAM-1) for the same ligands: CD155 (poliovirus receptor, PVR) and CD112 (Nectin-2 or PVRL2), expressed on APCs, T cells and some non-hematopoietic cell types like tumor cells." (PMID 34335585, 2021). "Moreover, the positive correlations between CCDC137 expression and immunosuppressive genes, such as TGFB1, NECTIN2, LGALS9, LAG3, and IL10RB, indicate the key role of CCDC137 in regulating tumor immunology, macrophage polarization, and CAFs formation." (PMID 34055889, 2021). "In addition, DNAM-1 expressed on the Vγ9Vδ2 T cells recognizes its ligands nectin-2 and polyoma virus receptor (PVR) that are widely expressed in tumor cells, which helps Vγ9Vδ2 T cells target tumor cells." (PMID 32413966, 2020). "TIGIT inhibitory function is mediated by binding to its ligand the poliovirus receptor (PVR, CD155), and poliovirus receptor-relate 2/Nectin-2 (PVRL2, CD112) which are present on the surface of APCs and non-hematopoietic cells including tumor cells." (PMID 32714317, 2020). "Two of these ligands, Necl-5 (usually termed CD155 or PVR) and Nectin-2 (CD112), frequently expressed on different types of tumor cells, are recognized by a group of receptors expressed on T and NK cells that exert opposite functions after interacting with their ligands." (PMID 31234588, 2019). "Co-activation by CD226 may play an important role in NK cell-defense against cancer since nectin-2 and CD155 are often overexpressed on tumor cells." (PMID 30759143, 2019). "Our data show the following: 1) This subpopulation of tumor cells only express nectin-2, not the other two major receptors (HVEM or nectin-1)." (PMID 29765544, 2018). "Kaplan-Meier survival analysis showed that poor differentiation, larger maximum tumor size, high TNM stage, lymph node metastasis and invasion, and positive Nectin-2 and DDX3 expression are significantly correlated with the shorter survival in PDAC cases (P < 0.05, P < 0.01, or P < 0.001)." (PMID 26294807, 2015). "K562 tumor cells express ligands for receptors promoting natural cytotoxicity (Nectin-2/PVR for DNAM-1; MICA/B/UBLP1 for NKG2D), but do not express the 2B4 ligand CD48 or classical HLA-A, B, C, and non-classical HLA-E." (PMID 23508354, 2013). "In silico analysis (Gene Expression Omnibus GSE127465) indicated that NECTIN2 was expressed in tumor cells, whereas TIGIT was predominantly expressed in T cells, suggesting that the NECTIN2/TIGIT axis may play a critical role in LUAD development and modulation of antitumor immune response." (PMID 40371640, 2025). "Among these, cell adhesion molecules such as Nectin-2 (PVRL2) and Nectin-4 (PVRL4) have emerged as potential molecular candidates due to their roles in tumorigenesis, epithelial integrity, and immune modulation as tumor-specific ligands for the immune checkpoint receptor TIGIT." (PMID 40699695, 2025). "PVR/TIGIT, NECTIN2/CD226, and FAM3C/PDCD1 were relatively more strongly expressed in Plac1+ epi‐CD4+ T cells than Plac1− epi‐CD4+ T cells and PVR was specific for Plac1+ tumor cells, which was subsequently validated in HNSCC cells in vitro and in the TMA cohort by mIF." (PMID 40056047, 2025). "They receive an activation signal and become activated, but they also receive negative signals from PVRIG, which is strongly engaged with NECTIN-2, which might limit anti-tumor activation." (PMID 36672396, 2023). "Because PVR and NECTIN2 can both act on TIGIT, compared to the currently popular PDL1/PDLD1 blockers, TIGIT may not only reverse the exhaustion state of CD8 T cells but may also improve the tumor immunosuppressive microenvironment to a certain extent." (PMID 36685571, 2022).
tumor (continued). "In addition to the pivotal role played by adhesion molecules (i.e., LFA-1 and CD2) in the NK cell interaction with target cells, engagement of DNAM1, a co-stimulatory receptor specific for Nectin-2 (CD112) and PVR (CD155), contributes to the response against tumor and virus-infected cells." (PMID 28261220, 2017). "Importantly, adjacent non-cancerous tissues expressed more nectin-2 than tumor tissues." (PMID 37568798, 2023). "Two ligands for TIGIT, CD155 (PVR) and CD112 (PVRL2, nectin-2), are expressed on APCs, T lymphocytes, and on non-hematopoietic cell types including tumor cells." (PMID 39273326, 2024). "TIGIT can bind to the receptors CD155 (poliovirus receptor-PVR), CD112 (PVRL2, nectin-2), and CD113 (Nectin-3) in immune cells, non-immune cells, and tumor cells, resulting in T cell activation and suppression of cytotoxicity." (PMID 34631507, 2021). "To compare the in vivo therapeutic effect of Baco-1 and FusOn-H2 against tumors that only express nectin-2 but not HVEM or nectin-1, we implanted A375 tumor cells to the right flank of NOD-SCID mice." (PMID 29765544, 2018). "Our data suggest the existence of a subpopulation of tumor cells that only express the nectin-2 but not the other receptors, and that only the HSV-2 (FusOn-H2) but not HSV-1 (Baco-1) based oncolytic virus can spread cell to cell in these tumor cells." (PMID 29765544, 2018). "The authors suggest that the difference in baseline serum nectin-2 levels between CRC patients and the healthy control group could be due to a higher expression of this molecule within the tumor, although this was not investigated." (PMID 37958883, 2023).
cancer (107 papers, 2012 to 2026). A tumor composed of atypical neoplastic, often pleomorphic cells that invade other tissues. "Nectin-2 and Nectin-4 are cell adhesion molecules associated with the progression of various cancers." (PMID 40699695, 2025). "Moreover, protein-protein interaction network analysis demonstrated that cancer cells expressing NECTIN2 were associated with T cell function through the coinhibitory receptor TIGIT, which promotes T cell dysfunction for immune evasion." (PMID 40371640, 2025). "Our study focuses on LSCC, providing new insights into the roles of Nectin-2 and Nectin-4—both of which remain relatively underexplored in this particular cancer type." (PMID 40699695, 2025). "Regarding the key interaction between T cells and cancer cells, increased expression of ligand-receptor pairs MIF_TNFRSF10D, CD55_ADGRE5, CD226_NECTIN2, CCL3L1_CCR1, and CCL3_CCR1 was observed." (PMID 39986271, 2025). "A recent study has demonstrated that cancer cells expressing NECTIN2 promote an immunosuppressive environment through T cell dysfunction." (PMID 40371640, 2025). "Recent studies have demonstrated that cancer cells expressing NECTIN2 inhibit T and natural killer (NK) cell function by interacting with T cell immunoglobulin and ITIM domain (TIGIT)." (PMID 40371640, 2025). "NECTIN2 (CD122) is overexpressed in various cancers, and TIGIT is commonly expressed in most Tregs in humans as a co‐inhibitory molecule." (PMID 39601163, 2024). "There are several studies, mainly concerning gastrointestinal cancers, which suggest nectin-2 involvement in cancers’ development and the impact on prognosis." (PMID 37568798, 2023). "TIGIT competes with inhibitory receptors KIR2DL5A and PVRIG and activating receptor CD226 (DNAM-1) to bind ligands CD155 (PVR) and CD112 (Nectin-2 or PVRL2) which are commonly expressed on cancer cells and antigen-presenting cells (APCs)." (PMID 37345049, 2023). "Nectin-2 was found to be expressed in 54.7% of cancers, which was a significantly higher percentage than in the control groups." (PMID 37568798, 2023). "IHC staining revealed that 68 cancers (42.7%) were classified as high-expressing, whereas 91 tumors (57.2%) had low nectin-2 expression." (PMID 37568798, 2023). "Previous studies have investigated the potential of Nectin-2 and Nectin-4 as biomarkers and treatment targets in various cancer types." (PMID 37174031, 2023). "The results showed that the expression levels of nectin-1 and nectin-2 genes in HCC tissues were higher compared to those in normal tissues adjacent to cancer from all patients (p < 0.001)." (PMID 36059705, 2022). "DNAM-1 is an activating receptor that upon ligation with PVR and Nectin-2, triggers NK cell-mediated cytotoxicity against various cancer cells." (PMID 36419901, 2022). "Recently, it has been shown that nectin-2 protein overexpressed in cancer cells functions as an immune checkpoint by binding to the nectin-2 protein receptor (PVRIG) of NK and cytotoxic T cells." (PMID 36293219, 2022). "The checkpoint inhibitor TIGIT (T cell immunoreceptor with immunoglobulin and ITIM domain) plays a critical role in immune evasion of cancers via binding CD112 (PVRL2 or nectin-2), one of two TIGIT ligands." (PMID 35681785, 2022). "Nectin-2 was found to be overexpressed on MM PCs, and both PVR and nectin-2 expression were associated with poor prognosis in cancer." (PMID 35087536, 2021). "CADM3 and CADM4 were upregulated in most cancers, whereas NECTIN2 was downregulated in most cancers." (PMID 34925438, 2021). "DNAM-1 recognizes two ligands belonging to the Nectin family, CD155 (PVR) and CD112 (Nectin-2), which are widely expressed on various tissues and cancers." (PMID 35008589, 2021). "DNAM-1 recognizes two ligands, CD155 (poliovirus receptor, PVR) and CD112 (Nectin-2), that are widely expressed by cancer cells." (PMID 34712615, 2021). "It binds to its ligand (CD112 or PVRL2/nectin-2) and inhibits the strength with which T cells and NK cells respond to cancer." (PMID 34507594, 2021).